NRBF2 (nuclear receptor binding factor 2)
Description:
May modulate transcriptional activation by target nuclear receptors. Can act as transcriptional activator (in vitro). Involved in starvation-induced autophagy probably by its association with PI3K complex I (PI3KC3-C1). However, effects has been described variably. Involved in the induction of starvation-induced autophagy. Stabilizes PI3KC3-C1 assembly and enhances ATG14-linked lipid kinase activity of PIK3C3 (By similarity). Proposed to negatively regulate basal and starvation-induced autophagy and to inhibit PIK3C3 activity by modulating interactions in PI3KC3-C1. May be involved in autophagosome biogenesis. May play a role in neural progenitor cell survival during differentiation (By similarity).
Synonyms: NRBF-2; COPR; DKFZp564C1664; FLJ30395; COPR1; COPR2
Tractability: PROTAC: ubiquitination databases record sites on it; its protein half-life has been measured.
Gene: Protein-coding gene on chromosome 10 (63,133,247 to 63,155,031, forward strand). Ensembl gene ENSG00000148572.
Subcellular location: Nucleus; Cytoplasm; Cytoplasmic vesicle; Cytoplasmic vesicle, autophagosome
Subcellular location (Human Protein Atlas): Cytosol; Nucleoplasm
Pathways (Reactome):
Gene expression (Transcription): Nuclear Receptor transcription pathway
Gene Ontology:
Molecular function: protein binding
Biological process: autophagy; response to endoplasmic reticulum stress
Cellular component: cytoplasm; cytoplasmic vesicle; phosphatidylinositol 3-kinase complex, class III; nucleoplasm; nucleus; autophagosome
Genetic constraint (gnomAD): Loss-of-function variants: 8 observed, 19.62 expected, observed/expected ratio (o/e) 0.41, 90% interval 0.24 to 0.74. The upper end of that interval is the gene's LOEUF score, 0.74, which puts it in group 3 of 6, group 1 being the genes least tolerant of losing a copy. Missense variants: 237 observed, 296.52 expected, observed/expected ratio (o/e) 0.8, 90% interval 0.72 to 0.89. Synonymous variants: 89 observed, 103.77 expected, observed/expected ratio (o/e) 0.86, 90% interval 0.72 to 1.02.
Homologues: Orthologues: chimpanzee NRBF2 (99% identical), macaque NRBF2 (99% identical), dog NRBF2 (92% identical), pig NRBF2 (92% identical), rat AABR07072761.1 (91% identical), rat Nrbf2 (91% identical), guinea pig NRBF2 (90% identical), mouse Nrbf2 (89% identical), rabbit NRBF2 (88% identical), tropical clawed frog nrbf2 (55% identical), zebrafish nrbf2b (47% identical), Drosophila melanogaster CG42554 (17% identical).
Diseases named in the same sentence as NRBF2 in open-access papers:
NRBF2 is named in the same sentence as 21 diseases in open-access papers, as found by Europe PMC text mining. Sharing a sentence is not in itself a finding about the gene and the disease. The quoted sentences say what the papers report.
Alzheimer disease (6 papers, 2021 to 2026). A progressive, neurodegenerative disease characterized by loss of function and death of nerve cells in several areas of the brain leading to loss of cognitive function such as memory and language. "In Alzheimer’s disease, NRBF2 was identified to play a considerable role in regulating Alzheimer’s disease-associated protein degradation by modulating autophagy." (PMID 34530854, 2021). "The autophagy associated gene NRBF2 is known to have a reduction of expression in the human brain with Alzheimer’s disease (the seventh cause of death worldwide)." (PMID 34691152, 2021). "NRBF2 gene is known to be associated with Alzheimer’s disease, which some researchers have hypothesized to be a human-specific disorder." (PMID 34691152, 2021). "NRBF2 has been reported to be necessary for learning and memory, as well as cognitive impairment in Alzheimer’s disease (AD) patients." (PMID 40013119, 2025). "Autophagy regulatory proteins such as beclin-1, PARK 2/parkin and nuclear receptor binding factor 2 (NRBF2) are dysregulated in Alzheimer’s disease." (PMID 37627261, 2023). "However, the role of NRBF2 in autophagosome maturation has only been explored in colitis and Alzheimer’s disease." (PMID 34530854, 2021). "NRBF2 is also linked to Alzheimer disease (AD) as it mediates autophagic degradation of amyloid beta precursor protein (APP) and its protein level is reduced in brains of 5xFAD transgenic AD mice." (PMID 41162841, 2026). "The expression levels of NRBF2, along with BECN1, PIK3C3 and PIK3R4, are reduced in Alzheimer disease (AD) post mortem brains." (PMID 33459128, 2021). "In addition, studies of NRBF2 in Alzheimer’s disease revealed that NRBF2 plays an important role in regulating the degradation of APP C-terminal fragments by modulating autophagy and could be a potential therapeutic target for Alzheimer’s disease." (PMID 34530854, 2021).
Anxiety (3 papers, 2019 to 2025). Intense feelings of nervousness, tension, or panic often arise in response to interpersonal stresses. "Using open field (OF), light-dark (LD) box and elevated-plus maze (EPM) tasks, we observed that anxiety-related behavior was unchanged in young NRBF2-KO animals, suggesting that ventral hippocampal functions are unaffected in these mice." (PMID 31775806, 2019). "Subsequently, we investigated the potential influence of NRBF2 depletion on locomotor and anxiety-like behaviors by assessing behavioral changes in NRBF2-KO and wild-type (WT) mice using an open field test (OFT), elevated plus maze (EPM) test, and light-dark (LD) box test." (PMID 40013119, 2025). "Depletion of NRBF2 impaired memory acquisition, short-term, and long-term memory without causing any anxiety-like behavior." (PMID 40013119, 2025). "Moreover, loss of NRBF2 does not affect motor abilities or anxiety-like behaviors in mice, but has been shown to induce a depression-like phenotype." (PMID 40013119, 2025). "Specifically, our study demonstrates that NRBF2-KO mice develop memory deficits through multiple cognition assays, i.e. working memory (RAM), reference memory (CFC) and recognition memory (OLT), while displaying minor change in anxiety-related behavior based on OF, LD and EPM studies." (PMID 31775806, 2019).
Cognitive impairment (3 papers, 2019 to 2025). Abnormal cognition is characterized by deficits in thinking, reasoning, or remembering. "This study offer new insights into the role of NRBF2 and highlight the potential of targeting NRBF2 as a therapeutic strategy for addressing cognitive deficits associated with various disorders." (PMID 40013119, 2025). "Our data not only implicates NRBF2 deficiency as a risk factor for cognitive impairment associated with AD, but also support the idea of NRBF2 as a potential therapeutic target for AD." (PMID 31775806, 2019). "Our data suggest that loss of NRBF2 functions in the hippocampus impairs memory in mice and may contribute to the cognitive impairment associated with AD." (PMID 31775806, 2019). "In addition, NRBF2 may be a potential therapeutic target for cognitive impairment." (PMID 34530854, 2021).
colitis (3 papers, 2021 to 2023). Inflammation of the colon. "Our recent study found that autophagy-related gene NRBF2-deficient mice were more susceptible to DSS-induced colitis, exhibiting more pronounced intestinal inflammation and apoptotic cell aggregation." (PMID 37152076, 2023). "Previously, we found that NRBF2-deficient macrophages displayed impaired efferocytosis ability, which increased the susceptibility of mice to dextran sulfate sodium salt (DSS)-induced colitis." (PMID 37152076, 2023).
depression (2 papers, 2023 to 2025). "Moreover, loss of NRBF2 disrupts the neurogenesis-related protein network and causes exhaustion of aNSC pool, leading to the depression-like phenotype." (PMID 37644025, 2023). "Considering that overexpression of NRBF2 produced an antidepressant-like effect, NRBF2−/− mice were employed to investigate whether NRBF2 deficiency could induce depression-like behavior." (PMID 37644025, 2023). "Then, we asked whether chronic stress-induced deficits of NRBF2 in the DG were associated with the impairment of AHN in the rodent model of depression." (PMID 37644025, 2023). "To confirm the response of NRBF2 expression under chronic stress conditions, we employed other animal models of depression, including chronic unpredictable stress (CUS)- and chronic corticosterone (CORT)-induced depression." (PMID 37644025, 2023). "Collectively, these results suggest that overexpression of NRBF2 in the DG ameliorates CSDS-induced depression-like behavior in an AHN-dependent manner." (PMID 37644025, 2023). "In the present study, we discovered a previously unknown role for NRBF2 in the pathophysiology of depression via the regulation of AHN." (PMID 37644025, 2023). "Accordingly, we investigated whether aNSCs-specific overexpression of NRBF2 could ameliorate the chronic stress-induced depression-like behavior." (PMID 37644025, 2023). "Collectively, these results indicate that the ATG14L-containing PtdIns3K complex contributes to NRBF2-dependent autophagy in aNSCs and then restores the defective AHN in chronic stress-induced depression." (PMID 37644025, 2023). "However, whether and how NRBF2 regulates AHN in chronic stress-induced depression remains unclear." (PMID 37644025, 2023). "Pharmacological inhibition of VPS34 activity suppressed NRBF2-dependent autophagy and AHN in the DG, which facilitated the susceptibility of mice to stress, while specific overexpression of NRBF2 in DG aNSCs ameliorated CSDS-induced AHN impairment and depression-like behavior via inducing autophagy." (PMID 37644025, 2023). "Similarly, we observed a decrease in the expressions of NRBF2, LC3-II, and p62 proteins in the DG of CUS- and CORT-treated mice, accompanied by depression-like behavior." (PMID 37644025, 2023). "Our results showed that temozolomide abrogated NRBF2 overexpression-induced antidepressant-like and proneurogenic effects in CSDS-exposed mice, providing evidence that AHN is a crucial target of NRBF2-mediated regulation of depression-like behavior." (PMID 37644025, 2023). "Furthermore, restoring the expression of NRBF2 in aNSCs rescued chronic stress-induced AHN impairment and depression-like behavior while suppressing AHN was sufficient to abolish the antidepressant-like effect of NRBF2 overexpression." (PMID 37644025, 2023).
amyloidosis (1 paper, 2020). A disorder characterized by the localized or diffuse accumulation of amyloid protein in various anatomic sites. "Moreover, overexpression of NRBF2 reduced the amyloidosis of APP, and inhibition of NRBF2 could increase the amyloidosis of APP in AD cell models." (PMID 32998479, 2020).
breast carcinoma (1 paper, 2020). "Likewise, SMAD1 is negatively correlated with brain-specific relapse and expressed at slightly lower levels in basal-like tumors, while Nuclear Receptor Binding Factor 2 (NRBF2) is positively correlated with brain-specific relapse and expressed at similar levels across breast cancer subtypes." (PMID 32143622, 2020).
dementia (1 paper, 2019). Loss of intellectual abilities interfering with an individual's social and occupational functions. "In summary, our findings identify progressive decline in the expression of NRBF2 and NRBF2-associated autophagy complex in specific brain regions of AD patients, which correlates with clinical dementia progression." (PMID 31775806, 2019).
Insulin resistance (1 paper, 2024). Increased resistance towards insulin, that is, diminished effectiveness of insulin in reducing blood glucose levels. "Our in vitro studies demonstrated that NRBF2 knock-down had detrimental effects in Pods, GECs, MCs and PTCs and, in contrast, indicated that increased NRBF2 expression in podocytes protected against actin remodelling induced by insulin resistance." (PMID 39562547, 2024). "Given that NRBF2 has no prior links to kidney function or insulin resistance, we next investigated the role of NRBF2 in kidney cell lines." (PMID 39562547, 2024).
memory impairment (1 paper, 2019). "Our study also provides evidence that restoration or modulation of NRBF2 and perhaps its associated kinase complexes activities may represent a new therapeutic strategy for improving memory impairment related to AD." (PMID 31775806, 2019). "Therefore, the lack of NRBF2-related functions in the hippocampus primarily accounts for the memory impairment in the mutant mice." (PMID 31775806, 2019).
ZIKV infection (1 paper, 2021). "Three robust patterns were identified: genes, such as HSPA5, that were upregulated in DENV infection and downregulated in ZIKV and VEEV infections; genes like NRBF2 that were upregulated only during ZIKV infection; and genes, such as SERP1, that were downregulated only in VEEV infection." (PMID 33788849, 2021).
cancer (2 papers, 2021 to 2022). A tumor composed of atypical neoplastic, often pleomorphic cells that invade other tissues. "Since the increase in NRBF2 due to radiation promoted GBM aggressiveness, regulating NRBF2 activation is important for cancer treatment." (PMID 36333468, 2022). "BuHyun Youn at Pusan National University, Busan, and HyeSook Youn at Sejong University in Seoul, South Korea, and coworkers found that after radiotherapy, cancer cells showed higher levels of NRBF2, a protein that triggers autophagy, and were more aggressive." (PMID 36333468, 2022). "An increase in NRBF2 levels activates autophagy, which leads to radioresistance since autophagy supplies the nutrients required by cancer cells." (PMID 36333468, 2022). "To verify this in human cancers, we investigated the role of NRBF2 in vivo using the DepMap database." (PMID 36333468, 2022). "As such, NRBF2 is a poorly studied target, but considering the known functions of NRBF2, it holds the potential to be a contributing factor in the autophagy process for promoting cancer survival." (PMID 36333468, 2022). "Since NRBF2 was also involved in the aggressiveness of cancer cells, it was confirmed that lidoflazine could alleviate this malignant effect." (PMID 36333468, 2022). "Furthermore, when NRBF2 levels were evaluated in other carcinomas, the highest expression level was observed in GBM." (PMID 36333468, 2022). "Although the role of autophagy in EMT may depend on the cellular context considering its dual role in cancer, this could be strong evidence that altered metabolism by NRBF2 may affect migration and invasion, contributing to autophagy-mediated cancer aggressiveness." (PMID 36333468, 2022).
tumor (1 paper, 2022). "Although the size of the tumor decreased in the IR group, it was confirmed that the expression of the proliferation markers Ki67 and NRBF2 was increased in the surviving tumor cells." (PMID 36333468, 2022).
NRBF2 also shares sentences with these, for which no sentence is quoted: acne (1 paper); autoimmune disease (1); brain tumor (1); glioblastoma (1); infection (1); inflammatory bowel disease (1); neuroblastoma (1); subarachnoid hemorrhage (1).